DENND3 (DENN domain containing 3)
Description:
Guanine nucleotide exchange factor (GEF) activating RAB12. Promotes the exchange of GDP to GTP, converting inactive GDP-bound RAB12 into its active GTP-bound form. Regulates autophagy in response to starvation through RAB12 activation. Starvation leads to ULK1/2-dependent phosphorylation of Ser-472 and Ser-490, which in turn allows recruitment of 14-3-3 adapter proteins and leads to up-regulation of GEF activity towards RAB12 (By similarity). Also plays a role in protein transport from recycling endosomes to lysosomes, regulating, for instance, the degradation of the transferrin receptor and of the amino acid transporter PAT4. Starvation also induces phosphorylation at Tyr-858, which leads to up-regulated GEF activity and initiates autophagy (By similarity).
Synonyms: KIAA0870
Tractability: PROTAC: ubiquitination databases record sites on it.
Gene: Protein-coding gene on chromosome 8 (141,117,278 to 141,195,808, forward strand). Ensembl gene ENSG00000105339.
Subcellular location: Cytoplasm
Subcellular location (Human Protein Atlas): Cytosol; Vesicles
Pathways (Reactome):
Vesicle-mediated transport: RAB GEFs exchange GTP for GDP on RABs
Gene Ontology:
Molecular function: guanyl-nucleotide exchange factor activity
Biological process: endosome to lysosome transport; protein catabolic process; regulation of Rab protein signal transduction
Cellular component: cytosol; cytoplasm
Genetic constraint (gnomAD): Loss-of-function variants: 75 observed, 112.9 expected, observed/expected ratio (o/e) 0.66, 90% interval 0.55 to 0.81. The upper end of that interval is the gene's LOEUF score, 0.81, which puts it in group 3 of 6, group 1 being the genes least tolerant of losing a copy. Missense variants: 1,221 observed, 1,509.5 expected, observed/expected ratio (o/e) 0.81, 90% interval 0.77 to 0.85. Synonymous variants: 602 observed, 630.27 expected, observed/expected ratio (o/e) 0.96, 90% interval 0.89 to 1.02.
Homologues: Orthologues: chimpanzee DENND3 (97% identical), macaque DENND3 (89% identical), guinea pig DENND3 (79% identical), mouse Dennd3 (79% identical), pig DENND3 (77% identical), rat Dennd3 (77% identical), dog DENND3 (72% identical), tropical clawed frog dennd3 (60% identical), zebrafish dennd3a (50% identical), zebrafish dennd3b (18% identical), Caenorhabditis elegans denn-4 (14% identical), Drosophila melanogaster Crag (13% identical). Paralogues in human: DENND4C (18% identical), DENND4A (17% identical), DENND4B (15% identical).
Diseases named in the same sentence as DENND3 in open-access papers:
DENND3 is named in the same sentence as 7 diseases in open-access papers, as found by Europe PMC text mining. Sharing a sentence is not in itself a finding about the gene and the disease. The quoted sentences say what the papers report.
breast carcinoma (1 paper, 2022). "Seven genes were shared between prostate and positive breast cancer responders (TRNT1, NUFIP1, TDG, HSPA8, OTUD6B, RBM12, and DENND3)." (PMID 35520391, 2022).
diabetes (1 paper, 2025). "Additionally, 7 CpG sites annotated to MAN2A2, ABCG1, DENND3, NCOR2, BAIAP2 and CPT1A were linked to changes in diabetes status." (PMID 39827095, 2025). "Notably, among the seven CpG sites liked to the diabetes progression, five showed a negative correlation with gene expression levels, including cg23436042, cg11183227 (MAN2A2), cg06500161 (ABCG1), cg06710464 (BAIAP2), and cg17058475 (CPT1A), while cg08788930 (DENND3) and cg11311053 (NCOR2) did not." (PMID 39827095, 2025).
Hirschsprung disease (1 paper, 2021). Hirschsprung disease (HSCR) is a congenital intestinal motility disorder that is characterized by signs of intestinal obstruction due to the presence of an aganglionic segment of variable extent in the terminal part of the colon. "In the context of pathology, among the genes recently associated with Hirschsprung disease (HSCR), showing impaired enteric nervous system development, WES analysis identified mutations affecting the GEF DENND3, typically involved in intracellular trafficking by activation of RAB12." (PMID 34124035, 2021).
iron overload (1 paper, 2021). "Of the 32 patients with primary iron overload (23 were males and 9 were females), non-HFE variants were detected in 31 (31/32, 97%), including 8 pathogenic variants in HJV, 7 pathogenic variants in SLC40A1, 8 likely pathogenic variants in SUGP2 and 5 likely pathogenic variants in DENND3 cases." (PMID 34583728, 2021).
Sepsis (1 paper, 2020). Sepsis is defined as life-threatening organ dysfunction caused by a dysregulated host response to infection. "Gene entities shared between sepsis and severe sepsis response hubs are; TDRD9 – LIN7A, GPR84 – ENTPD7, PYCT1A and ZDHHC19, CD177 – DDAH2 and RGL4, SLC16A3 – DENND3 and MBD6, MYL9 – CMTM5, ITGB3, ITGA2B, NRGN, SELP and TREML1." (PMID 32318053, 2020).
DENND3 also shares sentences with these, for which no sentence is quoted: prediabetes (1 paper); tumor (1).